MOG (myelin oligodendrocyte glycoprotein)
Diseases named in the same sentence as MOG in open-access papers (continued):
Sharing a sentence is not in itself a finding about the gene and the disease.
epilepsy (10 papers, 2017 to 2025). A brain disorder characterized by episodes of abnormally increased neuronal discharge resulting in transient episodes of sensory or motor neurological dysfunction, or psychic dysfunction. "Upon literature review, we found that she had an overlap syndrome reported as benign, unilateral, cerebral cortical encephalitis with epilepsy associated with the MOG-antibody, recently reported in four men, aged from 23 to 39 years." (PMID 29064441, 2017). "In terms of imaging manifestations, it is necessary to distinguish whether MRI abnormalities are brain damage caused by epilepsy or MOG." (PMID 37520572, 2023). "A recent study identified CSF MOG‐IgG positivity in 4/282 (1.4%) controls (MS, intracranial metastases, epilepsy, cord infarct), 66/74 (89%) seropositive MOGAD patients, and 9/73 (12%) seronegative patients with a potential MOGAD phenotype." (PMID 39073255, 2024). "In particular, a diagnosis of adult CCE with anti-MOG antibody should be considered when young patients present with fever, headache, epilepsy, or unilateral (or bilateral) cortical or sulcus FLAIR hyperintensity." (PMID 37520572, 2023). "In general, cortical damage caused by epilepsy is characterised by hyperintensity on DWI, which indicates cytotoxic oedema, while cortical damage caused by MOG-Ab-related CCE is usually indicated by abnormal hyperintensity on FLAIR." (PMID 35046784, 2021). "Furthermore, a subset of patients in the remaining patients with AQP4 antibody-seronegative NMOSD who presented with fever, headache, epilepsy, and imaging meningeal involvement were found to be positive for the myelin oligodendrocyte glycoprotein (MOG) antibody." (PMID 33750325, 2021).
meningitis (10 papers, 2010 to 2025). A disorder characterized by acute inflammation of the meninges of the brain and/or spinal cord. "Aseptic meningitis represents a rare and underrecognized phenotype of myelin oligodendrocyte glycoprotein (MOG) antibody-associated disease (MOGAD)." (PMID 41208985, 2025). "Since opportunistic infections and HIV-associated meningitis are easily detected by an elevated CSF cell count, elevated CSF anti-MOG antibodies could aid the clinician in the sometimes difficult diagnosis of HAND." (PMID 21083890, 2010). "According to the proposed diagnosis criteria of MOGAD, this patient exhibited a typical pattern of meningitis, as evidenced by infection-like symptoms, CSF findings, and a positive serum MOG antibody at the titer of 1:100." (PMID 41262622, 2025). "Subsequently, anti-MOG positivity in patients with a variety of cortical and meningeal disease presentations has been reported, indicating a broader spectrum of meningo-cortical manifestations in MOGAD that we review herein." (PMID 36341089, 2022). "Histologically, GATA3-tg mice had decreased levels of meningitis and demyelination in the spinal cord, and anti-inflammatory cytokine profiles immunologically, however both groups developed similar levels of MOG-specific lymphoproliferative responses." (PMID 24463292, 2014). "Meningitis is rarely reported as the primary clinical manifestation of both anti-aquaporin-4 (AQP4)/ anti-myelin oligodendrocyte glycoprotein (MOG) antibody-negative NMOSD (NMOSDneg)." (PMID 33750325, 2021).
Anxiety (9 papers, 2016 to 2025). Intense feelings of nervousness, tension, or panic often arise in response to interpersonal stresses. "This approach can be extended to MOG‐Ab patients, as pain interference and anxiety are the only significant factors associated with fatigue." (PMID 32187851, 2020). "Within MOG‐Ab patients, pain interference and anxiety were associated with fatigue, in a positive direction." (PMID 32187851, 2020). "We investigated the anxiety-like phenotype associated with MOG-induced central inflammation in presymptomatic EAE mice." (PMID 27589957, 2016). "Overall, our study confirmed that reduced GMV and cortical thickness in the right SFG and MOG may underlie the progression from anxiety to CAD in young women." (PMID 40959147, 2025). "Our results suggest that high anxiety was associated with deactivation in the right fusiform gyrus, right parahippocampal gyrus, and bilateral MOG, all known to be related to appraisal of potential threats concerning information related to immediate danger for survival in humans." (PMID 28473796, 2017). "Within MOG‐Ab patients, pain interference score (P < 0.001) and anxiety (P = 0.001) were significant independent variables." (PMID 32187851, 2020).
aseptic meningitis (9 papers, 2021 to 2026). Inflammation of the membranes surrounding the brain and spinal cord without a bacterial pathogen. "Myelin oligodendrocyte glycoprotein antibody-associated isolated aseptic meningitis is a novel and underrecognized clinical phenotype." (PMID 41208985, 2025). "This condition has therefore been gradually recognized as MOG antibody-associated aseptic meningitis (MOGAM) and integrated into the phenotypic spectrum of MOGAD." (PMID 41208985, 2025). "Recently, sporadic cases of aseptic meningitis associated with MOG-Abs have been reported." (PMID 41208985, 2025). "Besides, aseptic meningitis associated with leptomeningeal enhancement may be an atypical phenotype of MOG-EM." (PMID 33419414, 2021). "Seven patients presenting with isolated aseptic meningitis were excluded from this study following the filtering process, three of whom tested positive for MOG-Abs." (PMID 41515652, 2026). "We report a case of prolonged aseptic meningitis in which anti-MOG antibodies were subsequently detected." (PMID 41497944, 2025). "Isolated MOG antibody-associated aseptic meningitis (MOGAM), defined as MOGAM without neuroparenchymal lesions, is a rare and underrecognized phenotype." (PMID 41208985, 2025). "This study aimed to describe the clinical characteristics of MOG antibody-associated aseptic meningitis (MOGAM) in pediatric patients without neuroparenchymal lesions." (PMID 41208985, 2025). "This was emphasized in a review of twelve patients with MOG antibody positivity and aseptic meningitis in the absence of brain parenchymal lesions, which the authors referred to as MOG antibody-associated aseptic meningitis (MOGAM)." (PMID 36341089, 2022).
influenza (9 papers, 2014 to 2026). An acute viral infection of the respiratory tract, occurring in isolated cases, in epidemics, or in pandemics; it is caused by serologically different strains of viruses (influenzaviruses) designated A, B, and C, has a 3-day incubation period, and usually lasts for 3 to 10 days. "In the present study, HBPDS, which is an herbal medicine for treating influenza and for enhancing immune activity in Oriental medicine, displayed a beneficial effect in MOG-induced EAE." (PMID 26444423, 2015). "Here, we present the first report of a patient with anti-MOG antibody-positive LETM after influenza infection." (PMID 25434485, 2014). "Literature also confirms that influenza and EBV participate in the pathogenesis of anti-MOG ADEM, having a predictive value in the relapsing multiphasic course risk." (PMID 35624969, 2022). "Furthermore, to gain a deeper understanding, it’s vital to include other infection-control groups in comparisons, such as examining the incidence rates of MOG-ON and AQP4-ON during influenza seasons." (PMID 38988608, 2024).
teratoma (9 papers, 2016 to 2025). A non-seminomatous germ cell tumor characterized by the presence of various tissues which correspond to the different germinal layers (endoderm, mesoderm, and ectoderm). "A retrospective study collected 17 cases with tumors within two years of MOGAD onset, indicating potential paraneoplastic associations with teratoma, ovarian tumor, and melanoma, with the strongest association to teratoma, in which MOG protein expression was detectable in tumor tissue biopsy." (PMID 41459522, 2025). "Histological results showed the presence of nerve tissue expressing MOG protein and immune cell infiltration in the teratoma." (PMID 35370624, 2022). "Our findings endorse the suggestion to test for MOG-IgG in patients with demyelinating disorders of the CNS and co-existing teratoma included in the recent international consensus recommendations on MOG-IgG testing." (PMID 33078290, 2021). "A paraneoplastic etiology of MOG-EM in this case is further supported by the immune cell infiltration of the tumor and the fact that resection of the teratoma was followed by disappearance of MOG-IgG in the long-term course." (PMID 33078290, 2021). "Histopathology revealed neural tissue expressing MOG protein and accompanying immune cell infiltration within the teratoma, suggesting a possible paraneoplastic origin of MOG-EM in this case." (PMID 33078290, 2021). "In addition, most of the patients with PNSs (including AQP4-IgG+ NMOSD, MOG-EM) had full recovery or almost full recovery after removal of teratoma and immunotherapy." (PMID 35651803, 2022). "Given the recent observations on a strong association of NMDAR-IgG-positive encephalitis with teratoma as well as reports on paraneoplastic NMOSD, studies systematically evaluating the prevalence of teratoma in MOG-IgG-positive adult women may be warranted." (PMID 33078290, 2021). "Considering the latency of less than 1 year between removal of the tumor and ON, a humoral immune response directed against ectopic MOG expressed in the teratoma may have triggered remote neurologic autoimmunity in our patient." (PMID 33078290, 2021). "Notably, two prior MOGAD patients with concurrent teratoma had MOG immunostaining in the tumor suggesting that paraneoplastic MOGAD may occasionally occur." (PMID 39932929, 2025). "However, in patients with MOG-EM associated with OT, none of them experienced recurrence after teratoma resection." (PMID 35651803, 2022). "Although there was no teratoma in our study, it is noteworthy that MOG staining was attempted on a variety of tumor tissues, including small cell lung cancer, which is high risk for paraneoplastic syndrome, and all results were negative." (PMID 39932929, 2025). "Several studies have shown that early teratoma resection helps to reduce the recurrence of anti-NMDAR encephalitis, and interestingly, previously published cases suggest that this condition seems to also be applicable for AQP4-IgG+ NMOSD and MOG-EM." (PMID 35651803, 2022). "Two and four months after the second attack and 18 and 20 months after removal of the teratoma, MOG-IgG had turned negative according to three assays." (PMID 33078290, 2021). "However, different from our patient, MOG expression within the teratoma was not studied in the previous cases." (PMID 33078290, 2021). "However, few patients who were double positive for MOG-IgG and NMDAR-IgG had teratomas, suggesting that tumors may not be the cause of antibody coexistence syndrome." (PMID 36009058, 2022). "While, to the best of our knowledge, the presence of MOG in teratomas has not been investigated so far, expression of CNPase, an oligodendrocyte marker, has been described in mature teratomas, and several reports on oligodendrogliomas arising in mature teratomas exist." (PMID 27802825, 2016).
type 1 diabetes (9 papers, 2015 to 2025). "The presence of MOG antibodies in pediatric demyelination and other neurological diseases and their absence in type I diabetes, highlights that these antibodies are markers of demyelination and not immune dysregulation." (PMID 29064441, 2017). "Native MOG antibodies were present in 47% of children with a demyelinating event (ADEM or clinically isolated syndrome), 6.9% of children with other neurological diseases, and absent in healthy controls as well as adults with MS and children with type I diabetes mellitus." (PMID 29064441, 2017).
brain inflammation (8 papers, 2012 to 2023). "In fact, selective loss of MOG was identified as a serologic marker of inflammatory brain disease." (PMID 24632812, 2014). "After intranasal delivery, these curcumin-exosomes were taken up by the microglial cells and induced their apoptosis, thus preventing LPS-induced brain inflammation and myelin oligodendrocyte glycoprotein (MOG)-induced autoimmune responses in an EAE model." (PMID 36143453, 2022).
Myelopathy (8 papers, 2019 to 2025). Myelopathy is an descriptive term, referring to pathology leading to a neurologic deficit related to the spinal cord. "Myelopathy with positive serum MOG antibodies was present in both of these cases, but one had a well-controlled HIV infection while the other was seroconverting at the time of presentation." (PMID 37845760, 2023). "This is more commonly seen in idiopathic transverse myelitis (5%), paraneoplastic myelopathy (35%), myelin oligodendrocyte glycoprotein antibody-associated disease (MOGAD), and GFAP-IgG, glycine, and glutamic acid decarboxylase-65 receptor-associated myelopathy." (PMID 36388234, 2022). "In addition, only 17 of 41 patients were tested for MOG-IgG, which may have been because some patients underwent their initial evaluation for myelopathy before being assessed at our center between 2018 and 2023 and before MOG-IgG assays became more widely available in 2017." (PMID 39442039, 2025). "Only two (28.6%) of seven children in the ADEM with MOG-abs group presented with symptoms of myelopathy compared to all seven (100%) children in the ADEM without MOG-abs group (P = 0.035)." (PMID 33329345, 2020). "This is in keeping with historical reports of children with ADEM (who were likely to have MOG-Ab) and myelopathy on MRI with no clinical signs to support the myelopathy." (PMID 30671648, 2019).
rheumatoid arthritis (8 papers, 2022 to 2024). A chronic, systemic autoimmune disorder characterized by inflammation in the synovial membranes and articular surfaces. "Known glycan self-antigens are MOG for MS, Myelin oligodendrocyte glycoprotein antibody-associated disease (MOGAD) and NMO/NMOSD; MAG for human demyelinating neuropathy; GM1, GD1a, GT1a and GQ1b for GBS; the latter also for BBE; and N-acetylglucosamine-6-sulfatase (GNS) for Rheumatoid Arthritis." (PMID 35806376, 2022).
Seizure (8 papers, 2019 to 2026). A seizure is an intermittent abnormality of nervous system physiology characterized by a transient occurrence of signs and/or symptoms due to abnormal excessive or synchronous neuronal activity in the brain. "A recent meta-analysis revealed that the probability of acute epileptic seizures in patients with MOG antibody disease is generally 20.5%." (PMID 40538658, 2025).
Alzheimer disease (7 papers, 2014 to 2024). A progressive, neurodegenerative disease characterized by loss of function and death of nerve cells in several areas of the brain leading to loss of cognitive function such as memory and language. "This case provides us with new thoughts into the production of MOG-IgG and the possible pathologic mechanism of MOG-IgG-associated disease (MOG-AD) and simultaneously further confirms the interaction between EBV and changes of CSF biomarkers of Alzheimer's disease (AD)." (PMID 36530610, 2022).
autoimmune disease of the central nervous system (7 papers, 2018 to 2025). "Myelin oligodendrocyte glycoprotein antibody-associated disease (MOGAD) is an autoimmune disorder of the central nervous system, characterized by seropositive MOG antibodies." (PMID 40098969, 2025).
Behçet's disease (7 papers, 2020 to 2025). "Another patient, who also presented with neurological Behcet’s disease symptoms, was found to be MOG-IgG positive in remission (1:128)." (PMID 35370624, 2022).
Cognitive impairment (7 papers, 2018 to 2025). Abnormal cognition is characterized by deficits in thinking, reasoning, or remembering. "Region of interest‐based surface analysis specified reduced cortical thickness in the adjacent pericalcarine and orbitofrontal regions in myelin oligodendrocyte glycoprotein antibody‐associated disease, as well as reduced temporal cortical thickness in patients with cognitive impairment (n = 10)." (PMID 39054631, 2024). "In a questionnaire survey based upon retrospective paediatric-onset ADS cases in Japan, clinicians reported specific cognitive impairment in approximately 4 % of MOG lgG cases, similar rates to that of seronegative groups." (PMID 39243465, 2024). "We found that aberrant DC and FC were mainly distributed in the AMYG.L, bilateral MOG, INS.L, bilateral PFC and IPG.L, which are associated with cognitive impairment and emotional symptoms." (PMID 30534056, 2018). "Recent research has investigated long-term cognitive impairment and disability as a potential sequalae of pediatric-onset ADS patients who test positive for MOG-Ab, termed MOGAD." (PMID 39243465, 2024). "Our patient presented initially with cognitive impairment and focal neurological deficits without optic nerve or spinal cord involvement and the initial MOG-IgG titer was low, warranting cautious differential diagnosis before confirming MOGAD." (PMID 41459522, 2025).
Arthritis (6 papers, 2015 to 2020). Inflammation of a joint. "It will be interesting to further investigate whether LS-102, in addition to its effects on inducing synovial fibroblast apoptosis, suppresses T-cell activation and CD4 T-cell differentiation into Th1 and Th17 in mice during collagen-induced arthritis as well as MOG-induced EAE." (PMID 27417417, 2016). "Accordingly, carbidopa mitigated myelin oligodendrocyte glycoprotein peptide fragment 35–55 (MOG-35-55) induced experimental autoimmune encephalitis (EAE) and collagen induced arthritis in animal models." (PMID 28898256, 2017).
autoimmune optic neuritis (6 papers, 2009 to 2024). An autoimmune form of optic neuritis. "In a similar approach, MOG-TCR transgenic mice suffer from spontaneous autoimmune optic neuritis to some degree." (PMID 20142992, 2009).
Lyme disease (6 papers, 2020 to 2025). Lyme disease (named after the towns in the USA where the disease was first identified) is a bacterial infection caused by Borrelia burgdorferi. "All patients – those with VZV infection with CNS involvement and those with neuroborreliosis – were negative for serum MOG-IgG." (PMID 34737756, 2021).
neuritis (6 papers, 2018 to 2025). A neuropathy arising from inflammation of one or more nerves. "Optic nerves of the sham-immunized control group showed normal histology, whereas MOG immunization resulted in a severe infiltration of inflammatory cells, confirming an established neuritis in 92% of analyzed optic nerves/animals." (PMID 29514678, 2018). "However, 2D2xCD19-BMHCIIxIgHMOG mice were completely resistant to both optic nerve inflammation and spontaneous EAE despite a substantial reconstitution of the CD4 T cell compartment with MOG-specific T cells as reported." (PMID 29944721, 2018).
neurological autoimmune diseases (6 papers, 2019 to 2025). "Recently, several studies have revealed that the proportion of Bregs was significantly lower in many neurological autoimmune diseases than in healthy individuals, such as MS, NMOSD, MOG-AD, and MG." (PMID 36781561, 2023).
primary progressive MS (6 papers, 2015 to 2025). "It is unclear if patients with primary progressive MS (PPMS) or secondary progressive MS (SPMS) should routinely be tested for MOG-IgG." (PMID 29554927, 2018). "To obtain more definite data on the role of MOG-IgG in chronic progressive CNS demyelination, we decided to test a large cohort of patients previously diagnosed with primary progressive MS (PPMS) or secondary progressive MS (SPMS) for MOG-IgG." (PMID 29554927, 2018).